MMP2 (matrix metallopeptidase 2)
Diseases named in the same sentence as MMP2 in open-access papers (continued):
Sharing a sentence is not in itself a finding about the gene and the disease.
ameloblastoma (13 papers, 2008 to 2024). The most common odontogenic tumor, arising from the epithelial component of the embryonic tooth and usually affecting the molar-ramus region of the mandible or maxilla. "RECK protein expression was negatively associated with MMP-2 protein expression in ameloblastoma (r = -0.431, P < 0.01)." (PMID 19995435, 2009). "Among MMPs, MMP-2 has been closely associated with ameloblastoma invasion." (PMID 19995435, 2009). "However, few reports have delineated the combinatorial role and association of RECK and MMP-2 in ameloblastoma." (PMID 19995435, 2009). "Therefore, this study investigated the combinatorial role and association of RECK and MMP-2 in ameloblastoma." (PMID 19995435, 2009). "Activation of EGFR can promote cell migration and invasion in ameloblastoma cells by enhancing MMP2 and MMP9 activity." (PMID 39100096, 2024). "•Unidentified factors from osteoblast conditioned medium induced MMP-2 production and stimulate proliferation and cellular motility of ameloblastoma cells." (PMID 35243014, 2022). "Osteoblast-derived factors induced the production of MMP-2 by ameloblastoma cells which degrade ECM." (PMID 35243014, 2022). "The invasive properties of ameloblastoma cells and their ability to resorb bone were investigated by assessing the expression of MMP-2, MMP-9, RANK, and RANKL16 prior to initiation of invasion." (PMID 34916549, 2021). "The ameloblastomas showed a high frequency of unmethylated MMP-2 and MMP-9, whereas the healthy gingival samples presented a sharp prevalence of methylated MMPs." (PMID 22866959, 2012). "All of the ameloblastoma samples showed expression of MMP-2 and MMP-9 proteins, as verified by zymography." (PMID 22866959, 2012). "Overexpression of MMP-2 and MMP-9 was associated with the infiltrative behaviour of ameloblastomas, as well as that of several malignant neoplasms." (PMID 22866959, 2012). "The suppression of MMP-2 activity was able to inhibit the invasiveness of ameloblastoma cells in vitro." (PMID 22866959, 2012). "The aim of this study was to characterize the relationship between RECK and MMP-2 expression and the clinical manifestation of ameloblastoma." (PMID 19995435, 2009). "Our and other studies also showed that the high expression and activity of MMP-2 is related to a more aggressive behavior in ameloblastoma." (PMID 19995435, 2009). "Similar findings have been described in our and other studies of ameloblastoma, indicating that high MMP-2 expression and activity is related to a more aggressive infiltrative behavior in ameloblastoma." (PMID 19995435, 2009). "MMP-2 protein expression was significantly higher in ameloblastoma and ameloblastic carcinoma compared with KCOT (P < 0.01)." (PMID 19995435, 2009). "Previous studies performed by our group revealed that the MMP-2 inhibitor, Ro31-9790, inhibited adhesion and invasion of ameloblastoma cells in primary cell cultures." (PMID 18588710, 2008). "Previous studies have shown that ameloblastomas have an elevated expression of MMP-2, MMP-9, and vascular endothelial growth factor (VEGF), and are void of or have an abnormal expression of E-cadherin and TIMP-2." (PMID 18588710, 2008). "Both MMP-2 siRNA and TIMP-2 overexpression inhibited MMP-2 activity and the in vitro invasiveness of ameloblastoma." (PMID 18588710, 2008). "Primary cultures of ameloblastoma cells expressed cytokeratin (CK) 14 and 16, and MMP-2, but only weakly expressed CK18 and vimentin." (PMID 18588710, 2008). "siRNAs against MMP-2 significantly inhibited MMP-2 mRNA expression and MMP-2 protein levels in primary ameloblastoma cell cultures." (PMID 18588710, 2008). "Ameloblastoma cells that were immunopositive for MMP-2 showed green fluorescence in the cytoplasm and red fluorescence in the cell nucleus under a fluorescent microscope." (PMID 18588710, 2008). "This study was conducted to address the role of matrix metalloproteinase-2 (MMP-2) in the invasiveness of ameloblastomas." (PMID 18588710, 2008).
ameloblastoma (continued). "Among the proteases thought to be involved in ameloblastoma invasion, attention has focused on MMP-2." (PMID 18588710, 2008). "After transfection of ameloblastoma cells with various doses of pRNA-MMP-2, the activity of MMP-2 was significantly decreased compared with the three control groups (p < 0.05)." (PMID 18588710, 2008). "The invasion assay showed that the ability of ameloblastoma cells to invade the lower surface of the filter through the Matrigel was significantly inhibited in both MMP-2 knockdown or TIMP-2 overexpression cells compared to the control cultures." (PMID 18588710, 2008). "MMP2 expression in all ameloblastoma tumouroids supported invasiveness of ameloblastoma cells." (PMID 36452176, 2022). "While AM-3 cells spontaneously produced high amount of MMP-9 and had potential to increase MMP-9 production in response to Wnt-3a, this study demonstrated that AM-3 ameloblastoma cells showed higher expression of MMP-2 by the treatment of MC3T3-E1 osteoblast CM." (PMID 35243014, 2022). "Ameloblastoma cells increased expression of MMP-2 and -9 and RANK temporally in 3D compared to 2D." (PMID 34916549, 2021). "Perhaps this could explain the similar expression levels of MMP-2 mRNA in ameloblastomas and healthy gingiva." (PMID 22866959, 2012). "Therefore, the purpose of this study was to investigate the association between MMP-2 and MMP-9 methylation and their mRNA transcription and protein expression in ameloblastomas." (PMID 22866959, 2012). "The ameloblastomas presented an unmethylated profile of MMP-2 and MMP-9 genes compared to gingiva." (PMID 22866959, 2012). "All ameloblastomas showed positive expression of MMP-2 and MMP-9 proteins." (PMID 22866959, 2012). "RECK may participate in the invasion, recurrence and malignant transformation of ameloblastoma by regulating MMP-2 at the post-transcriptional level." (PMID 19995435, 2009). "This study was designed to test the hypothesis that MMP-2 activity is involved in the invasiveness of ameloblastomas and that inhibition of MMP-2 is a useful approach for treating ameloblastomas." (PMID 18588710, 2008). "To investigate whether inhibition of MMP-2 activity will suppress the invasiveness of ameloblastoma cells, we knocked down MMP-2 by RNA interference or overexpressed TIMP-2." (PMID 18588710, 2008). "The goal of this study was to determine whether inhibition of MMP-2 activity was capable of suppressing the local invasiveness of human ameloblastoma cells." (PMID 18588710, 2008). "TIMP-2 overexpression inhibited MMP-2 activity in ameloblastoma cells." (PMID 18588710, 2008). "This study provided evidence that inhibition of MMP-2 activity may serve as a novel therapeutic target in the clinical management of ameloblastoma." (PMID 18588710, 2008). "Analysis of the effect of MMP-2 siRNA or TIMP-2 overexpression on ameloblastoma cell invasion." (PMID 18588710, 2008). "In summary, these data indicate that siRNA targeting of MMP-2 mRNA or TIMP-2 overxpression using a plasmid-based system effectively inhibited the activity of MMP-2 in ameloblastoma cells, which subsequently resulted in reduced ameloblastoma cell invasiveness in vitro." (PMID 18588710, 2008). "This led to the supposition that the suppression of the local invasiveness of ameloblastoma cells may be related to inhibition of MMP-2 activity." (PMID 18588710, 2008). "Neutralizing agents for IL-1 or MMP-2 may have therapeutic use to control ameloblastoma locally." (PMID 35243014, 2022). "In summary, lower or no expression of RECK and increased expression of MMP-2 may be associated with worse clinical outcomes in ameloblastoma, and RECK may help modify the behavior of ameloblastomas by regulating MMP-2 at the post-transcriptional level." (PMID 19995435, 2009). "Low or no RECK expression and increased MMP-2 expression may be associated with negative clinical findings in ameloblastoma." (PMID 19995435, 2009).
ameloblastoma (continued). "Therefore, we investigated whether siRNAs targeted at MMP-2 are capable of inhibiting the activity of MMP-2 in ameloblastoma cells." (PMID 18588710, 2008). "Several studies also demonstrated that MMPs like MMP-1, MMP-2, MMP-7, MMP-9 and MMP-14 are involved in ECM degradation in the invasion of ameloblastoma [16,21,22,]." (PMID 35243014, 2022). "The ameloblastoma samples showed higher immunoexpression of HIF-1α, MMP-2, VEGF, and VEGFR-2 when compared to the dental follicles and calcifying odontogenic cysts." (PMID 33067558, 2020). "We investigated the methylation status of the genes MMP-2 and MMP-9 in addition to mRNA transcription and protein expression in ameloblastomas." (PMID 22866959, 2012). "Relative expression levels of RECK mRNA were significantly lower in ameloblastoma than in KCOT (P < 0.01), but significantly higher for MMP-2 mRNA (P < 0.01)." (PMID 19995435, 2009). "Immunohistochemistry and reverse transcription-polymerase chain reaction (RT-PCR) were employed to detect the protein and mRNA expression of RECK and MMP-2 in keratocystic odontogenic tumor (KCOT), ameloblastoma and ameloblastic carcinoma." (PMID 19995435, 2009). "MMP-2 mRNA was detected in all KCOT, ameloblastoma and ameloblastic carcinoma samples, and strongly expressed in both ameloblastic carcinoma samples." (PMID 19995435, 2009). "Immunoreactivity for MMP-2 was mainly detected in prickle cells of KCOT, peripheral columnar or cuboidal cells of ameloblastoma and ameloblastic carcinoma cells." (PMID 19995435, 2009). "This was accomplished using an MMP-2 gene knockdown approach or TIMP-2 overexpression and subsequently detecting the relationship between MMP-2 activity and the local invasiveness of ameloblastoma cells." (PMID 18588710, 2008). "Further, zymography and reverse gelatin zymography assays revealed that pcDNA-TIMP-2 transfection decreased MMP-2 activity and increased TIMP-2 activity in ameloblastoma cells." (PMID 18588710, 2008). "MMP-2 siRNA and pcDNA-TIMP-2 each inhibited the invasion of ameloblastoma cells through the Matrigel compared to the mock, lipifectamine, and vector-transfected control cells." (PMID 18588710, 2008). "Plasmids containing either MMP-2 siRNA or tissue inhibitor of metalloproteinase-2 (TIMP-2) cDNA were created and subsequently transfected into primary ameloblastoma cells." (PMID 18588710, 2008). "In the present study, we hypothesised that methylation may regulate the expression of MMP-2 and MMP-9 in ameloblastomas." (PMID 22866959, 2012). "Methylation analysis was performed by both methylation-specific polymerase chain reaction (MSP-PCR) and restriction enzyme digestion to evaluate the methylation profile of MMP-2 and MMP-9 in 12 ameloblastoma samples and 12 healthy gingiva fragments, which were included as controls." (PMID 22866959, 2012). "Numerous studies have used siRNAs to analyze the function of MMP-2, but to date no studies have utilized this technique with ameloblastomas." (PMID 18588710, 2008). "Our results show higher immunoexpression of HIF-1α, MMP-2, VEGF, and VEGFR-2 in ameloblastomas when compared to calcifying odontogenic cysts and dental follicles, suggesting that the relationship between these proteins may contribute to the behaviour of this neoplasm." (PMID 33067558, 2020). "MMP-2 expression was significantly higher in ameloblastic carcinoma (100%) and ameloblastoma (84.06%) than in KCOT (18.75%, P < 0.01), but was not significantly different in primary ameloblastoma (82.22%) versus recurrent ameloblastoma (87.5%) or between histological types." (PMID 19995435, 2009). "Furthermore, our data suggest that MMP-2 expression in ameloblastomas may not be modulated by methylation because the methylation profile for this gene did not correlate with MMP-2 transcript levels in this odontogenic tumour." (PMID 22866959, 2012).
ameloblastoma (continued). "MMPs are well-studied in the case of ameloblastoma, however there is not much data on MMP-3 and most of the reported literature is on MMP-2, -7, and -9." (PMID 38226014, 2024). "MMP-2 mRNA expression was significantly higher in ameloblastoma compared with KCOT (P < 0.01), but was no different in recurrent ameloblastoma versus primary ameloblastoma." (PMID 19995435, 2009). "In ameloblastoma, protein expression in RECK and MMP-2 were inversely proportional (r = -0.431, P < 0.01), but mRNA expression of RECK and MMP-2 were not correlated (r = 0.367, P > 0.05)." (PMID 19995435, 2009). "However, pro-MMP-2 and pro-MMP-9 forms were not identified in ameloblastomas." (PMID 22866959, 2012).
cholesteatoma (13 papers, 2007 to 2025). A pathologic process characterized by the proliferation of keratinizing squamous epithelium resulting in the accumulation of keratin and cells in the middle ear and/or mastoid. "The decreased number of TIMP-2 and increased MMP-2 in patient groups compared with the control group are the cause of the intensive remodulation in patients with cholesteatomas." (PMID 38535082, 2024). "In an inflammatory environment, such as chronic otitis media with cholesteatoma, MMP-2 and MMP-9 cause pathologic bone degradation." (PMID 36837507, 2023). "In this study, we evaluated clinical samples to analyze the association of MMP2 mRNA expression level with different subtypes of cholesteatoma." (PMID 33778077, 2021). "The underlying mechanisms of MMP2 expression in cholesteatoma can be clarified by analyzing the expression levels of these genes." (PMID 33778077, 2021). "We then studied the association between the stages of cholesteatoma and tissue MMP2 mRNA expression level." (PMID 33778077, 2021). "In conclusion, our study revealed that MMP2 mRNA expression level is strongly associated with different subtypes of cholesteatoma." (PMID 33778077, 2021). "Our study reveals that MMP2 mRNA expression level is strongly associated with the subtypes of cholesteatoma." (PMID 33778077, 2021). "Metalloproteinases are enzymes capable of causing bone erosion, especially the MMP2, which has become object of correlation with cholesteatomas." (PMID 17505599, 2007). "The 19 cholesteatoma slides (8 of them were invasive) underwent an immunohistochemical technique for MMP2 detection, causing the reading of a qualitative MMP2 presence in the outer portion of the cholesteatoma." (PMID 17505599, 2007). "It was observed that MMP-9 and MMP-2 overexpression may be implicated in the molecular inflammatory pathways in cholesteatoma development." (PMID 37762439, 2023). "Notably, serum levels of MMP2 were reported to be associated with the degree of ossicle injury and invasion of cholesteatoma." (PMID 33778077, 2021). "Herein, we observed higher MMP2 mRNA expression level in the open type than in the closed type and in the pars tensa than in the pars flaccida type, which suggests that MMP2 mRNA expression level in the cholesteatoma tissue is strongly associated with specific subtypes of cholesteatoma." (PMID 33778077, 2021). "Cholesteatoma produces enzymesthat cause bone erosion like Matrixmetalloproteinase 2 (MMP2)." (PMID 17505599, 2007). "Remodeling factors matrix metalloproteinase 2 and 9 (MMP-2 and MMP-9) can cause bone destruction in the case of cholesteatoma." (PMID 38535082, 2024). "In the adult group, the mean number of MMP-2-positive cells in the cholesteatoma’s matrix was few to moderate (+/++), and in the perimatrix, few (+)." (PMID 38535082, 2024). "The remodeling factors MMP-2 and MMP-9 are associated with bone remodulation in the middle ear for patients with cholesteatoma." (PMID 36837507, 2023). "Matrix metalloproteinase-2 (MMP2) was previously reported to play an important role in cholesteatoma progression, by promoting bone destruction and keratinocyte infiltration." (PMID 33778077, 2021). "Our findings support this theory, as we demonstrated that open type of congenital cholesteatoma has shared pathology with pars tensa type of acquired cholesteatoma, in that they both have upregulated MMP2 mRNA expression level." (PMID 33778077, 2021). "Further studies are needed to address the effectiveness of MMP2 inhibition in alleviating cholesteatoma." (PMID 33778077, 2021). "In cholesteatoma, MMP-2 plays a major role in bone resorption and angiogenesis, which is one of the main factors under study when researchers analyze the aggressiveness of cholesteatoma." (PMID 34682191, 2021). "Firstly, although several past studies on cholesteatoma explored not only MMP2 but also IL-6, other MMPs, TREM-2, and EGFR, this study focused only on the expression of MMP2 mRNA." (PMID 33778077, 2021).